MPO (myeloperoxidase)
Diseases named in the same sentence as MPO in open-access papers (continued):
Sharing a sentence is not in itself a finding about the gene and the disease.
infection (continued). "When a pro-inflammatory milieu, triggered by an event such as infection, stimulates neutrophils to express MPO and PR3, these antibodies bind, activating neighboring neutrophils, causing excessive NET formation and subsequent endothelial cell damage." (PMID 36598752, 2023). "The number and proportion of neutrophils in peripheral blood increased during hypoxia, increased significantly after infection, and were significantly higher in the MPO−/−-infected mice than in the WT-infected mice." (PMID 38037141, 2023). "Results confirm the intracellular presence of this enzyme during T. brucei-infection, as MPO+Ly6G+ neutrophils formed clear foci." (PMID 37669943, 2023). "This makes MPO a valuable tool for studying the neutrophil function and activation in various physiological and pathological processes, including inflammation and infection." (PMID 37159591, 2023). "The level of intestinal MPO was increased in the WT mice under hypoxic conditions and increased significantly after infection." (PMID 38037141, 2023). "Analysis of endothelial parameters revealed that Hispanic ethnicity was positively correlated with VCAM-1 and MPO which corresponds to elevated levels of these markers seen in severe infection." (PMID 37598150, 2023). "Here, we report for the first time the dysregulated degranulation, specifically the release of MPO and elastase, in healthy human neutrophils as a result of direct infection and due to secreted factors from infected epithelial cells in vitro." (PMID 35203591, 2022). "Since CD16 shedding is associated with enhanced degranulation, we quantified secreted MPO and elastase in the supernatant 2 h post infection." (PMID 35203591, 2022). "MPO is more abundantly expressed in neutrophils than other blood immune cells and catalyses production of ROS, a potent microbicidal response to infection." (PMID 35769481, 2022). "The device produces a clear, purple, visible readout when it detects infection-related MPO activity." (PMID 36012396, 2022). "For example, during H9N2 infection, kaempferol alleviated pulmonary edema, lung wet/dry (W/D) weight ratio, pulmonary capillary permeability, myeloperoxidase (MPO) activity, and the numbers of inflammatory cells in the virus mice model." (PMID 36145539, 2022). "It is known that the increased generation of ROS in biological fluids as a result of infection is mainly the result of reactions catalysed by xanthine oxidase, myeloperoxidase, and nitric oxide synthase, which modulate the signalling cascade." (PMID 35456059, 2022). "Of note, frequencies of MPO+ ROS+ necrotic neutrophils were always higher in animals at day 25 post infection before treatment started." (PMID 35269694, 2022). "In “normal” inflammatory conditions (e.g., during infection), active molecules formed in the catalytic cycle are used to eliminate harmful substances, whereas MPO is harmful in chronic clinical or subclinical inflammatory conditions." (PMID 35419382, 2022). "NETs are webs of extracellular fibers composed of DNA with histones, myeloperoxidase (MPO) and neutrophil elastase (NE), which are important for immune response to infection but worsen inflammation when they persist." (PMID 35913450, 2022). "Several studies have demonstrated that the granulocyte enzyme myeloperoxidase can be used as a quantitative marker to measure the intestinal inflammation accompanying infection (73, –, 75)." (PMID 35100875, 2022). "We measured the amount of Myeloperoxidase (MPO) released by PMNs into the supernatants in response to infection as a proxy for mobilization of primary granules." (PMID 35402289, 2022). "At 35 days post infection, less MPO was measured in extracellular lung fractions, but more MPO was found in serum compared to 25 days post infection." (PMID 35269694, 2022).
infection (continued). "Post hoc data analysis revealed 3 patterns of enzymatic response associated with clear infection: at least one highly elevated enzyme, two moderately elevated (HNE, LYS) or at least one high (MPO) and one moderate (HNE or LYS)." (PMID 36292097, 2022). "Both at 6 and 24 h after infection, bacterial burdens, neutrophil recruitment, neutrophil activation (CD11b expression, MPO and elastase production in the BALF), and pro-inflammatory cytokines (IL-1β, IL-6 and TNF) levels were similar in both mouse strains." (PMID 35269409, 2022). "WT mice exposed to only OPC had higher MPO production compared to infected Il17ra−/− mice, which aligns with the high fungal burden in Il17ra−/− compared to immunocompetent WT mice that clear infection by this time point." (PMID 35628751, 2022). "The impact of neutrophil depletion on the ability of CCL3 treatment to boost infection control in diabetic wound was assessed by MPO analysis (i) and CFU count determination (h & j) in day 1 wounds." (PMID 35112667, 2022). "Humanized transgenic ZF with human myeloperoxidase (MPO) in neutrophils was created to investigate the roles of MPO during infection and inflammation." (PMID 36142160, 2022). "During infection, myeloperoxidase and elastase protein were released in the bronchoalveolar spaces at higher concentrations compared to C57BL/6 mice." (PMID 36685578, 2022). "Upon infection, neutrophils release chromatin fibers, known as neutrophil extracellular traps (NETs), together with high amounts of elastase, myeloperoxidase (MPO) and lactoferrin—one million of neutrophils can release up to 15 μg of LF." (PMID 36145610, 2022). "Infection of neutrophils resulted in an impairment of both MPO and elastase release, even though CD16 receptor shedding was upregulated." (PMID 35203591, 2022). "PMNs are the first cells to reach the site, and, therefore, MPO is one of the first enzymes to appear, responding from the beginning of the infection in an acute and almost immediate way." (PMID 35335191, 2022). "We found that PMNs released 7-fold more MPO upon infection with S. pneumoniae opsonized with heat inactivated immune sera compared to bacteria opsonized with naïve sera." (PMID 35402289, 2022). "The infection of C. perfringens caused a heightened tendency on the concentrations of LPS, IL-6, CRP and PCT (0.05 < P < 0.10), and an increase on the activity of MPO (P < 0.05) in serum of broilers." (PMID 35436978, 2022). "This is in line with the observation that mainly extracellular MPO activity is affected by infection and subsequent ABAH treatment." (PMID 35269694, 2022). "During infection, the bactericidal and fungicidal properties of MPO contribute to pathogen clearing inside the phagosome." (PMID 33916434, 2021). "Numerous studies have provided strong evidence for the extracellular presence of enzymatically active MPO at sites of infection and inflammation." (PMID 32661559, 2021). "We observed an increase of the concentration of IL-1β, TNF-α and MPO during the progression of the infection, which positively correlated with the concentration of PTX3 (P < 0.0001, P = 0.0018, P = 0.0139, respectively)." (PMID 34093560, 2021). "We observed an increase in myeloperoxidase enzyme activity in group 2903 when compared to group 1655 at 90 days of infection; the opposite was observed for NAG enzymatic activity." (PMID 34336715, 2021). "Relative to uninfected samples, placental plasma from tissues with evidence of chronic, inflammatory infection shows significantly elevated MPO levels." (PMID 34737733, 2021). "Based on observations with SG staining, which suggested that METs were induced due to infection, we proceeded to search for two proteins that have been described to be located in extracellular traps: Hit3Cit and MPO." (PMID 34683348, 2021). "To characterize the METs induced by infection with probiotics, we searched for the presence of Hit3Cit and MPO in the infected cells." (PMID 34683348, 2021).
infection (continued). "MPO is expressed in neutrophils, monocytes, and some tissue macrophages, and generates HOCl during inflammation and infection." (PMID 34502389, 2021). "One and 2 days post-infection, mice were injected with luminol that reacts with superoxide generated in phagosomes, reflecting the myeloperoxidase activity of tissue-infiltrating neutrophils." (PMID 34603295, 2021). "Studies have shown that infection by the influenza virus reduces the bactericidal ability of neutrophils in the lungs due to the reduced MPO activity and impaired digestion, and/or lethality of the secondary bacterial infection." (PMID 34472718, 2021). "The level of the granulocyte marker MPO in lung homogenate was also lower in vaccinated mice after challenge infection with C.tr." (PMID 34204170, 2021). "Hallmarks of cell death and inflammation, including cleaved caspase-1 and −3, gasdermin-D, neutrophil elastase, catalase, complement C3, and myeloperoxidase were validated in lung tissues on day 6 after infection via immunoblot." (PMID 34319784, 2021). "A. baumannii infection results in the recruitment of neutrophils to the infection site in order to combat the bacteria by releasing multiple molecules, including myeloperoxidase, reactive oxygen species (ROS), β-defensins, cytokines, and chemokines." (PMID 34829902, 2021). "MPO is elevated in infection and has been shown to contribute to the generation of dysfunctional HDL with impaired cholesterol efflux mediated by HDL." (PMID 34018068, 2021). "The temporary employment of additional chaperones in response to oxidative stress provides an efficient mechanism to specifically counteract and resist the strong oxidizing properties of MPO-derived hypohalous acids during infection or inflammation." (PMID 32661559, 2021). "Thus, it can be assumed that the MPO bound to the fungal cell surface may serve the pathogens to cause damage to the surrounding host tissue, which may be beneficial for the further infection propagation, especially when the fungal protection mechanisms are secured at the same time." (PMID 34685715, 2021). "Similar to DEFA1, MPO levels were unaltered during subclinical infection (p=0.85) while a significant increase was observed in the patients with mild (p=0.01) and severe (p=0.02) disease." (PMID 34746027, 2021). "LPS stimulation leads to a significant increase in MPO activity, which means that neutrophils accumulate at the site of infection." (PMID 34858427, 2021). "Of note, raised DEFA1 and MPO levels characterized symptomatic infections while elevated levels of calprotectin marked SARS-CoV-2 infections irrespective of clinical presentation." (PMID 34746027, 2021). "Tyrosine metabolism was found to positively correlate with both myeloperoxidase (MPO) and IL-8, which are essential for neutrophil responses during an infection." (PMID 34211479, 2021). "Using confocal microscopy, we identified the formation of METs from the first hours of infection, which were characterized by the presence of myeloperoxidase (MPO) and citrullinated histone (Hit3Cit)." (PMID 34683348, 2021). "For that purpose, eosinophils and neutrophils contain specific granules containing protoporphyrin-type proteins such as eosinophil peroxidase (EPO) and myeloperoxidase (MPO), respectively, which contribute directly to their anti-infection activity." (PMID 32906767, 2020). "The surveillance roles conducted by PMN consist mainly of their ability to migrate to the site of infection (chemotaxis), a respiratory burst and myeloperoxidase (MPO) release." (PMID 32640682, 2020). "Results show that MPO seems to be a sensitive marker of the condition of immune system activity of infected rabbits, as it by definition increases over the course of infection." (PMID 32899838, 2020). "Taken together these findings suggest that recruited neutrophils into the infection site potentially induce NETosis, which is dependent on MPO activity." (PMID 32391009, 2020).
infection (continued). "MPO therefore warrants investigation in the present study, as a potential biomarker for infection or monitoring the respiratory burst in patients post-FURS." (PMID 32795278, 2020). "Prenatal IA exposure to 7 days of LPS and to chronic 42 days infection by UP both provoked an influx of neutrophils (MPO-positive cells) in the intestine." (PMID 32256485, 2020). "129.Nlrc4–/– mice also exhibited dramatic cecum shrinkage and diarrhea, lost between 8% and 18% of their starting weight within 2 days of infection, and exhibited a massive increase in fecal MPO following infection." (PMID 33074100, 2020). "Regarding to inflammatory cells recruited to lung tissue, we also observed a diminished neutrophils migration into the lung parenchyma in ethanol-treated mice, by MPO measurement, at 24 hr after infection." (PMID 32701055, 2020). "Confirmation of the importance of MPO as part of the neutrophil’s armory to fight infection was confirmed by use of MPO knockout mice, in which killing of Candida albicans was defective." (PMID 33391268, 2020). "Our findings reveal that neutrophils recruited at infection site exhibit high MPO activity and undergo NETopathic cell death during active Ft infection." (PMID 32391009, 2020). "The rise in fecal MPO in mice receiving smaller inocula was delayed relative to previous infections with 5 × 107 CFU, suggesting that infectious dose correlates with disease onset." (PMID 33074100, 2020). "We did observe a slight but significant increase in fecal MPO levels at 1–3 days post-infection in these mice." (PMID 33074100, 2020). "In the present study, also we observed the transcript levels of MPO, a key host defense gene, was down-regulated both at 6 and 24 h post-infection." (PMID 32275661, 2020). "Changes to kidney (NGAL, Cystatin-C) and infection (MPO, PCT) biomarkers was quantified by means of ELISA, Biomerieux mini-vidas and Konelab 20 analysers." (PMID 32795278, 2020). "The infection with L. amazonensis stimulated significant increase in MPO compared with control, whereas treatment with NAC (200 mg/kg) notably reduced MPO activity when compared to vehicle." (PMID 31931804, 2020). "Although PR3-ANCA and MPO-ANCA are serological markers for AAV, the interpretation of PR3-ANCA and/or MPO-ANCA positivity should consider the possibility of protracted infection." (PMID 32624005, 2020). "We also showed the reduction in the MPO activity in divalent IgG-treated corneas at the late stage of infection, suggesting that this treatment approach induced low resolution of the inflammation." (PMID 30944709, 2019). "At 10 days post-infection, mice fed diets rich in omega-6 polyunsaturated fatty acids had increased F480-positive macrophages and myeloperoxidase-positive neutrophils and higher inflammatory cytokines at the site of infection compared to mice fed fish oil." (PMID 31484327, 2019). "Since ArcA regulates several important genes in response to ROS inside neutrophils, we determined the MPO activity in infected neutrophils at the same times post-infection used for transcriptional analyses, which provides an estimation of the HOCl production." (PMID 31866961, 2019). "TNF-α, IL-1β, MPO activity, and epidermal/dermal thickness increased in the infected paw, which confirmed the peripheral inflammation at the primary foci of this infection." (PMID 31138231, 2019). "Immunofluorescence images of brain sections revealed the presence of MPO-positive neutrophils at the injection site and in the ventricles 24 h after infection." (PMID 30971685, 2019). "Unlike MPO deficiency, those with CGD experience frequent life-threatening infections from a wide range of pathogens, and consequently, the role of MPO is less clear when observed in the context of other oxidative enzymes and compounds." (PMID 31002727, 2019). "The importance of effective MPO release is highlighted by the findings in MPO-knockout mice of increased prevalence of infections, prolonged inflammation, and shorter survival." (PMID 31134093, 2019).
infection (continued). "Information about rectal inflammation grading (e.g., myeloperoxidase, proinflammatory cytokines) would help in elucidating the complex interactions between infection, immunity and microbial local communities." (PMID 31681634, 2019). "Both compounds exhibited potent IC50 values (0,01 μM) against myeloperoxidase (MPO), a heme-enzyme present in human neutrophils that plays an important role in infection and inflammation." (PMID 31395797, 2019). "MPO activity was elevated in the liver of infected animals compared to the controls at all post-infection times." (PMID 31653913, 2019). "In a series of proof-of-concept experiments we detected MPO activity in a variety of mouse models of infection and inflammation." (PMID 31695784, 2019). "The significant associations at 6 months included anti-flic IgA with astrovirus infection, anti-flic IgA with STEC (stx1, stx2) infection, MPO with Campylobacter infection, serum Reg 1b with ETEC ST infection, fecal Reg1 β with Giardia." (PMID 31442248, 2019). "In this study, we have generated a transgenic zebrafish line expressing fluorescently-labelled human MPO in zebrafish neutrophils, as a tool towards investigating the roles of MPO during infection and inflammation." (PMID 31002727, 2019). "L. amazonensis induced an increase of MPO activity in the ipsilateral side of the infection indicating neutrophil/monocyte recruitment." (PMID 31138231, 2019). "Controlled MPO release at the site of infection is of prime importance for its efficient activities." (PMID 29669993, 2018). "At 48h-post infection, the extent of inflammation as depicted by H&E and MPO staining was similar between WT and NKLAM-KO mice." (PMID 29518136, 2018). "Clarithromycin treated mice also showed significant reduction (P < 0.05) in MPO enzyme activity as compared to infection control group and FCP treated group." (PMID 29651276, 2018). "We extended those initial findings to now show that importantly, LGM2605 inhibits myeloperoxidase (MPO), the key enzyme in inflammatory cells such as macrophages and neutrophils that generates hypochlorous acid (HOCl) during inflammation and infection." (PMID 29498660, 2018). "During the first 4 wk of infection, MPO-specific bioluminescence was significantly higher in Δisp2/3-infected ears compared with WT." (PMID 29097502, 2018). "The results showed a significant increase of MPO activity in the duodenum only at 12h post infection (G12: 0.1856 ± 0.0143) (p<0.05) compared to the control group (0.1516 ± 0.0078)." (PMID 29324806, 2018). "In the present study we aimed to study the activation of T-cells, monocytes/macrophages and neutrophils during infection with P. falciparum by using sCD25, sCD14, sCD163 and MPO as markers of T-cell, monocyte/macrophage and neutrophil activation, respectively." (PMID 30563486, 2018). "LPS-induced increases in pulmonary MPO content tended to be enhanced as well, but only at 4 days post-infection." (PMID 29978355, 2018). "Results demonstrate that tissue levels of NAG and MPO were similar in ΔdblGATA-1 and WT mice after infection, suggesting that the accumulation of these cells in tissues was similar in these animals." (PMID 30687649, 2018). "Despite this increase in the MPO activity, our data shows that P. gingivalis is able to significantly inhibit its downstream product antimicrobial HOCl present at 2 h post-infection." (PMID 28725637, 2017). "We found that neutrophil recruitment to the lung during infection by S. pneumoniae or K. pneumoniae (measured by myeloperoxidase (MPO) levels) is unaffected by antibiotic treatment." (PMID 29142211, 2017). "MPO activity of the host cells was assayed and found to be positively affected by eATP treatment and/or infection." (PMID 28725637, 2017). "Myeloperoxidase was increased in skin of StingGt/Gt mice compared to WT mice at 8 and 18 hours following infection." (PMID 28704551, 2017).